AR (androgen receptor)
Diseases named in the same sentence as AR in open-access papers (continued):
Sharing a sentence is not in itself a finding about the gene and the disease.
prostate carcinoma (continued). "The AR LBD coactivator binding groove is a target of drugs to manipulate AR activity especially in the development of anti-prostate cancer drugs." (PMID 32158429, 2020). "Most AR-targeted genes or interacting pathways have been studied in prostate cancer, whereas understanding of AR signaling pathways in breast cancer and especially in TNBC remains relatively limited." (PMID 32587770, 2020). "Analysis of TCGA patient samples suggests the presence of patients with prostate cancer who have similar GR/AR expression profiles." (PMID 33303959, 2020). "For example, a study suggested that Erβ served as a tumor suppressor in prostate cancer by inhibiting the expression and activity of androgen receptor." (PMID 32054506, 2020). "A challenging aspect in treating prostate cancer is that even those patients who are treated with the new androgen receptor antagonists such as ENZ, after first-line therapy fails, also develop resistance to these drugs." (PMID 32802517, 2020). "Our results are consistent with other studies showing that another curcumin analog, ASC-J9, induces MDM2-mediated AR ubiquitination to inhibit prostate cancer, suggesting that AR is a critical player for anti-cancer effects of curcumin and its analogs." (PMID 31896509, 2020). "The drawback of these AR antagonists as therapeutics for prostate cancer is the drug resistance, which can be developed by reactivating or bypassing androgen receptor signaling pathway." (PMID 32456317, 2020). "In prostate cancer, the tumors are dependent on AR and androgen-deprivation therapy is a gold standard therapy in advanced prostate cancer." (PMID 32484822, 2020). "The androgen receptor (AR) dictates the transcriptional output that promotes proliferation and survival of prostate cancer cells." (PMID 32634370, 2020). "Historically most AR co-regulators were identified using prostate cancer cell lines, and, thus, were disproportionally or exclusively limited to epithelial cells." (PMID 32584883, 2020). "The interaction of endothelial cells with tumor cells has been shown to mediate AR-independent invasion of prostate cancer cells." (PMID 33425737, 2020). "DHX15 enhances androgen receptor (AR) transcriptional activity by stimulating Siah2-mediated ubiquitination, which contributes to the progression of prostate cancer." (PMID 33644083, 2020). "On the other hand, IGF1R usually co-expressed with androgen receptor in response to dihydrotestosterone (a male-sex hormone)-dependent prostate cancer cell proliferation." (PMID 32150843, 2020). "Castration-resistant prostate cancer is the lethal form of prostate cancer and most commonly remains dependent on androgen receptor (AR) signaling." (PMID 35582223, 2020). "The androgen receptor (AR) is a pivotal target for the treatment of prostate cancer (PC) even when the disease progresses toward androgen-independent or castration-resistant forms." (PMID 33374450, 2020). "Collectively, these data showed that brassicasterol from edible aquacultural H. abdominalis exerted an anti-cancer effect by dual-targeting AKT and AR signaling in prostate cancer." (PMID 32972001, 2020). "Both phosphorylation events promote the binding of STAT3 to AR, resulting in AR stabilization, which stimulates proliferation of prostate cancer cells." (PMID 31910742, 2020). "This discovery also opens a new therapeutic path and supports the rationale for using ESRP modulators in combination with AR antagonists for the treatment of advanced-stage prostate cancer to counteract the AR-antagonist-driven invasive phenotype." (PMID 32820253, 2020). "Androgen/androgen receptor (AR) signaling drives both the normal prostate development and prostatic carcinogenesis, and patients with advanced prostate cancer often develop resistance to androgen deprivation therapy." (PMID 32245249, 2020).
prostate carcinoma (continued). "We found that high expression levels of CRPC-Lncs are significantly more correlated with gene induction than repression, suggesting that CRPC-Lncs facilitate gene induction of other downstream targets as well as AR in prostate cancer tissues." (PMID 32704143, 2020). "Although FOXM1 signaling was amplified in mCRPC, FOXM1 signaling also appeared to play an important role in LNCaP cells, an AR-dependent prostate cancer cell line." (PMID 32629770, 2020). "Androgen receptor (AR) signaling pathway is necessary in the pathogenesis of prostate cancer, and there is a heightened interest in finding novel AR antagonists that target AR and its regulatory pathways." (PMID 33094102, 2020). "In prostate cancer, menin has been identified as an important co-factor for androgen receptor (AR) signaling by direct interaction with the N-terminal domain of the AR and recruitment of the MLL histone methyltransferase activity." (PMID 31947537, 2020). "Targeting the androgen receptor (AR) signaling is the mainstay treatment owing to the significance of AR in prostate cancer development." (PMID 32657763, 2020). "This has been further verified by the recent FDA approval of the other two second-generation AR antagonists, apalutamide and darolutamide, for the treatment of prostate cancer." (PMID 32456317, 2020). "The androgen receptor (AR) is a key molecule in the development and progression of prostate cancer (PC) and as such is a critical therapeutic target." (PMID 32324216, 2020). "While TNFα regulation via miR-130a already has been shown in cervical cancer cells by EGFP reporter assays and Western blotting, only indirect hints on a miR-130a regulation of AR existed so far in prostate carcinoma cell lines and mouse sertoli cells." (PMID 32272867, 2020). "Targeting activities of the androgen receptor (AR) by depriving it of androgen is a key therapeutic approach for prostate cancer; however, resistant tumors eventually occur and can progress to metastatic castration-resistant prostate cancer (CRPC)." (PMID 33322099, 2020). "Androgen receptor targeted therapies have emerged as an effective tool to manage advanced prostate cancer (PCa)." (PMID 31980029, 2020). "The role of AR in carcinogenesis has been studied more extensively in prostate cancer, in which there is compelling evidence for a crucial role of this pathway, due to its effects on prostate cell proliferation and differentiation." (PMID 32042320, 2020). "WNT and AR signaling cascades have also been shown to reciprocally inhibit each other in murine prostate cancer." (PMID 32630372, 2020). "AR antagonists (antiandrogens) inhibit these processes and are used for the treatment of advanced prostate cancer (PC)." (PMID 33374450, 2020). "The androgen receptor (AR) is a clinically validated target for the treatment of early‐ and late‐stage prostate cancer (PCa)." (PMID 32333502, 2020). "Because we filtered out alternatively spliced genes, which were also differentially expressed, we were able to discover a new and unique physiological impact of modulating AR signaling in prostate cancer cells." (PMID 32820253, 2020). "The similarities in the expression profile of TRPM4 and AR in DCIS, breast and prostate cancers suggest a connection of TRPM4 with AR signaling pathway in tumors, and this warrants future investigations." (PMID 32484822, 2020). "In this setting, potent androgen receptor (AR)-directed therapies (abiraterone and enzalutamide) have an important role in the therapeutic algorithm of advanced prostate cancer." (PMID 32580478, 2020). "Overall, evidence from analysis of splice array, RT-PCR and whole transcriptome data support our novel observation that modulation of AR signaling alters transcriptome of prostate cancer cells by regulating ASE." (PMID 32820253, 2020).
prostate carcinoma (continued). "Evolving knowledge of resistance mechanisms to AR targeted treatments will lead to additional research on designing more effective therapies for advanced-stage prostate cancer." (PMID 35582225, 2020). "YAP1 can bind to androgen receptor (AR) and affect the proliferation of prostate cancer epithelial cells, thus affecting the progression of prostate cancer." (PMID 32066485, 2020). "The clinical regimen of 2–3 months of neoadjuvant ADT prior to radiotherapy increases the expression of AR-Vs in prostate cancer patients." (PMID 32708219, 2020). "IL-23 produced by myeloid-derived suppressor cells (MDSCs) stimulate AR in prostate cancer cells in order to promote survival and proliferation during androgen deprivation therapy (ADT) and, therefore, promote progression to CRPC." (PMID 33076397, 2020). "We analyzed the structures, expressions, biological functions and clinical relevance of PMEPA1-e isoform and less characterized isoforms c and d in the context of prostate cancer and AR/TGF-β signaling." (PMID 32064040, 2020). "Sex hormone nuclear receptors, estrogen receptor α (ERa), progesterone receptor (PR), and androgen receptor (AR) are essential biomarkers in breast and prostate cancer pathology." (PMID 33266334, 2020). "As the androgen receptor (AR) pathway is critical for the progression and development of prostate cancer, androgen deprivation, which leads to the blockage of AR activity, is an effective therapy for the initial treatment of prostate cancer." (PMID 32629770, 2020). "The androgen receptor (AR) is the master regulator of prostate cancer (PCa) development, and inhibition of AR signalling is the most effective PCa treatment." (PMID 32908142, 2020). "Androgen receptor (AR) signaling is the major pathway in prostate cancer and thus androgen- deprivation therapy still remains the current principal treatment option for locally advanced and metastatic prostate cancer." (PMID 32226548, 2020). "The androgen receptor (AR) is the main driver in prostate cancer growth and progression and the most effective therapeutic agents are still directed against this pathway." (PMID 35582226, 2020). "Androgen receptor (AR), a steroid hormone receptor, is a well-recognized biomarker for predicting prognosis in prostate cancer." (PMID 33294126, 2020). "Second-generation AR antagonists are effective against some of these castration-resistant prostate cancers, but their structural variety is still limited." (PMID 32759847, 2020). "Examples include Glutathione S-transferase pi 1 (GSTP1), involved in DNA protection, androgen receptor (AR), in prostate cancer, estrogen receptor (ER) in breast cancer and adenomatous polyposis coli (APC) in colorectal cancer, among many others." (PMID 32365701, 2020). "The prostate specific antigen (PSA)—an androgen receptor which is widely employed as a marker in the detection of early prostate cancer—is regulated by androgens." (PMID 32872551, 2020). "These three second-generation AR antagonists not only offer patients with different stages of prostate cancer with alternative therapeutics, but also verified that AR signaling pathway plays a pivotal role in the progression of both CSPC and CRPC." (PMID 32456317, 2020). "Androgens play a fundamental role in cell growth and survival in androgen-receptor positive (AR+) prostate cancer cell lines, early-stages of prostate cancer, and even in normal prostate." (PMID 32210800, 2020). "To investigate the genotoxic effect of androgens on LNCaP human prostate cancer cells, which express functional AR, we enriched G1‐phase cells more than 90% by serum starvation for 48 hr and analyzed only cyclin‐A‐negative, G1‐phase cells." (PMID 32277721, 2020). "In prostate cancer, AR concentration in the serum/plasma or urine has already been correlated with diagnosis, prognosis, and outcome prediction." (PMID 31952272, 2020).
prostate carcinoma (continued). "In this study, we discovered a novel anti-tumor mechanism of maspin to repress androgen receptor (AR) transcription, which augmented the treatment efficacy of AR antagonist enzalutamide in prostate cancer." (PMID 33195208, 2020). "The study also demonstrates the correlation between AR and β-catenin playing a critical role not only in prostate cancer initiation but also in chemotherapy resistance progression." (PMID 35582225, 2020). "Targeting AR‐NTD to block FL‐AR and AR‐Vs with EPI in combination with ENZ resulted in synergistic inhibition of proliferation of ENZ‐resistant prostate cancer cells." (PMID 32734688, 2020). "Androgen receptor (AR)-regulated genes contribute to the initiation and progression of prostate cancer (PCa)." (PMID 33202977, 2020). "Most of the studies analyzing the role of AR have focused on prostate cancer, primarily in transformed cell lines but macrophages are vital in cancer development and metastasis." (PMID 32849595, 2020). "IRE1α‐XBP1s is also directly activated by androgen receptor signaling in prostate cancer cells and promotes their survival." (PMID 32310340, 2020). "Due to the diverse genomic aberrations in prostate cancer, multiple targeted therapies are being investigated for advanced prostate cancer, such as androgen receptor antagonists, AKT inhibitors, and PARP inhibitors." (PMID 31685947, 2020). "Prostate cancer is largely driven by androgens acting through the androgen receptor to give rise to proliferative and invasive cells." (PMID 33303959, 2020). "Only a few studies have tried to elucidate pathways in AR-prostate cancers, including the study by Bluemn and colleagues (2017)." (PMID 32019149, 2020). "The progression of prostate cancer (PCa) depends on androgens acting via the androgen receptor (AR), and therefore androgen deprivation slows disease." (PMID 32198885, 2020). "Studies to date have demonstrated that the AR exerts a regulatory effect on key metabolic pathways beyond its classical role as a hormone receptor during prostate cancer development and progression." (PMID 32927797, 2020). "They inhibited AR-positive prostate cancer cell proliferation in both in vitro and in vivo experiments and suppressed the growth of AR-positive prostate cancer cell-derived tumors." (PMID 32456317, 2020). "Initially, it remains an effective and essential paradigm in the treatment of metastatic CRPC, but AR reactivation drives prostate cancer to lethal CRPC phenotype in all patients despite effective testosterone suppression." (PMID 35582225, 2020). "Aberrant SOX2 expression is noted, particularly in castration-resistant prostate cancer cells where ligand activation of AR promotes a decrease in SOX2 expression as a result of direct binding of the AR to the SOX2 cis-enhancer region." (PMID 33339129, 2020). "While the majority of men with prostate cancer initially respond to androgen/AR-directed therapy, they inevitably develop castration-resistant prostate cancer (CRPC), as malignant cells develop therapeutic resistance." (PMID 32630372, 2020). "And CD147 was also reported to modulate androgen receptor activity through β-catenin pathway in prostate cancer." (PMID 32727598, 2020). "The two major types of treatments for castration resistant prostate cancer are inhibitors of synthesis of androgen ligand precursor (ketoconazole and abiraterone) and AR antagonists (enzalutamide and flutamide)." (PMID 32283832, 2020). "For example, the combination of olaparib with the androgen receptor (AR) inhibitors enzalutamide or bicalutamid is effective in HR-proficient prostate cancer due to suppression of HR gene expression." (PMID 32029455, 2020). "Most prostate cancers express a high level of AR and, thus, respond to androgen deprivation therapies." (PMID 33240734, 2020). "We assessed the dependence of LAR PDX tumor growth on AR signaling by the in vivo efficacy of enzalutamide, an androgen receptor inhibitor approved for the treatment of prostatic cancer." (PMID 32042320, 2020).
prostate carcinoma (continued). "In another study, PlncRNA-1 was found to enhance cell proliferation and induce EMT in prostate cancer through reciprocal regulation of AR, Her-2, and TGF-β signaling pathways." (PMID 32351538, 2020). "While Flii expression is found to be reduced within prostate cancer lesions compared to adjacent normal tissue, patients with high levels of AR expression but whose tumors were found to express high levels of Flii experienced better overall survival." (PMID 33330501, 2020). "As cellular proliferation is dependent on the androgen receptor function in prostate cancer, it is possible, that the significant link between elevated Ki67 labeling index and high TFAP2D expression is also androgen receptor driven." (PMID 32143573, 2020). "TXNDC5 directly interacts with the androgen receptor protein to increase its stability and enhance its transcriptional activity, thus stimulating the growth of castration-resistant prostate cancer." (PMID 31570854, 2020). "The role of this protein in prostate cancer cell proliferation was demonstrated by activating androgen receptor (AR)." (PMID 32537125, 2020). "WDR5 also binds to ACK1-mediated H4Y88ph and directs KMT2D to the promoter of the androgen receptor gene, thereby promoting its expression in castration-resistant prostate cancer." (PMID 33302406, 2020). "In particular, both the CCNA2 gene and FAS gene are activated by the androgen receptor that is the therapeutic target of prostate cancers." (PMID 32164534, 2020). "ARV-110 is an orally bioavailable AR PROTAC that entered into a clinical trial to treat patients with metastatic castrate-resistant prostate cancer (NCT03888612) in 2019." (PMID 32718354, 2020). "PSA was reported to be regulated by Androgen Receptor (AR) signaling and AR transcript levels were found to be reduced after the transient expression of miR-205 in androgen dependent VCaP and 22Rv1 prostate cancer cell lines." (PMID 32854238, 2020). "Androgen receptor (AR) plays a significant role in the development and progression of prostate cancer." (PMID 32055737, 2020). "Equally important, the successful clinical use of enzalutamide proves the notion that the second-generation AR antagonists can serve as hormonal therapeutics for three forms of advanced prostate cancer." (PMID 32456317, 2020). "HES6 also drives a critical AR transcriptional program to induce castration-resistant prostate cancer through the activation of an E2F1-mediated cell cycle network." (PMID 33681178, 2020). "WBSCR28 had not been well studied in human tumor, but it was repressed by androgen receptor in prostate cancer." (PMID 32351322, 2020). "The androgen receptor (AR) plays a critical role in prostate cancer (PCa) development and metastasis." (PMID 32825120, 2020). "ERa/p63/AR ColNu mIHCF revealed that ERa was as clear a marker of prostate cancer as p63 is for normal prostate epithelium." (PMID 33266334, 2020). "COX2 inhibitors suppress prostate cancer growth via a variety of pathways, including androgen receptor signaling pathway." (PMID 32824865, 2020). "Previous high-throughput approaches to study the role of microRNAs in prostate cancer include identification of miRs regulating the expression of the androgen receptor, and miRs that regulate proliferation." (PMID 32231998, 2020). "In prostate cancer, an activated nuclear AR binds to and reduces the DNA binding capacity of FOXO1 in an Akt-independent manner, affecting the expression of the proapoptotic genes, such as Fas." (PMID 32372224, 2020). "The clinical use of enzalutamide not only helps to better manage prostate cancer but also verifies that androgen receptor signaling continues to be one of critical driving forces for CRPC." (PMID 32456317, 2020). "The present study indicates that taxane compounds can exert a prostate cancer-specific anti-tumor function by inhibiting AR signaling." (PMID 32354165, 2020).